FAM24A (family with sequence similarity 24 member A)
Synonyms: AC073585.4
Tractability: Antibody: UniProt places it where antibodies can reach, with high confidence; UniProt predicts a signal peptide or a membrane-spanning region; its Gene Ontology location is reachable by antibodies, with medium confidence.
Gene: Protein-coding gene on chromosome 10 (122,910,610 to 122,913,111, forward strand). Ensembl gene ENSG00000203795.
Subcellular location: Secreted
Gene Ontology:
Cellular component: extracellular region
Genetic constraint (gnomAD): Loss-of-function variants: 2 observed, 3.38 expected, observed/expected ratio (o/e) 0.59, 90% interval 0.24 to 1.65. That is too few expected variants to judge how well the gene tolerates losing a copy. Missense variants: 109 observed, 138.8 expected, observed/expected ratio (o/e) 0.79, 90% interval 0.67 to 0.92. Synonymous variants: 46 observed, 50.55 expected, observed/expected ratio (o/e) 0.91, 90% interval 0.72 to 1.16.
Homologues: Orthologues: chimpanzee FAM24A (98% identical), macaque FAM24A (86% identical). Paralogues in human: FAM24B (63% identical).